CRP (C-reactive protein)
Diseases named in the same sentence as CRP in open-access papers (continued):
Sharing a sentence is not in itself a finding about the gene and the disease.
type 2 diabetes (continued). "Acute phase proteins (APPs), such as plasminogen activator inhibitor-1 (PAI-1), serum amyloid A (SAA), and C-reactive protein (CRP), are elevated in type-2 diabetes (T2D) and are routinely used as biomarkers for this disease." (PMID 35883605, 2022). "The purpose of this study was to evaluate the association between type 2 diabetes and the severity of periodontal disease using ABL and the hs-CRP value as indices." (PMID 35805792, 2022). "Recent studies reported that C-reactive protein as an acute phase reactant has close relationship with type 2 diabetes, as well as the inflammatory marker of cardiovascular diseases." (PMID 36588532, 2022). "Univariate analysis showed that type 2 diabetes was significantly associated with age, sex, body mass index, number of teeth, ABL, hs-CRP, and periodontal disease severity." (PMID 35805792, 2022). "A cohort of patients with poorly controlled Type 2 diabetes displayed hyperlipidemia, increased C-reactive protein, and blood glucose concentration, as well as excessively increased HbA1c." (PMID 33478094, 2021). "A controlled trial in 64 patients with type-2 diabetes found that 500 mg/day hesperidin for 6 weeks decreased both CRP and IL-6 concentrations from baseline values." (PMID 34249019, 2021). "Absolute neutrophil count and C-reactive protein at the time of admission were significantly elevated in the type-2 diabetes group." (PMID 34221008, 2021). "In patients with type 2 diabetes, serum PCT seems to be better correlated with cardiovascular risk than serum highly sensitive C-reactive protein which has previously been shown to be associated with cardiovascular diseases." (PMID 34725609, 2021). "In healthy patients with both type 1 and type 2 diabetes, insulin infusion (with dextrose to maintain euglycemia) leads to decreased reactive oxygen species, systemic cytokine gene expression and serum CRP levels." (PMID 33992101, 2021). "Elevated CRP was observed using simple linear regressions in patients with type II diabetes, higher cumulative joint scores, increased number of affected joints, as well as elevated uric acid, erythrocyte sedimentation rate, and leukocyte count." (PMID 34063875, 2021). "In conclusion, high serum CRP concentrations and high WBC counts, indicating overactivated immunity, were positively associated with MetS risk, primarily type 2 diabetes." (PMID 34371818, 2021). "A recent study showed that elevated salivary levels of C-reactive protein and TNF-α have been significantly associated with type 2 diabetes." (PMID 34829612, 2021). "In line, plasma levels of ALT, GGT and hs-CRP were significantly higher in male type 2 diabetic patients than healthy males." (PMID 33101209, 2020). "Findings were inconsistent regarding the effects of C-reactive protein and plasma homocysteine levels on type 2 diabetes in previous studies." (PMID 32895727, 2020). "Ginger supplementation reduced CRP in subjects with type 2 diabetes (1.6–3 g/d for 12 wk) and nonalcoholic fatty liver disease (2 g/d for 12 wk)." (PMID 32211803, 2020). "In response to elevated cytokines levels, the liver secretes C-reactive protein (CRP), a key marker of inflammation associated with several metabolic diseases including type 2 diabetes and cardiovascular diseases." (PMID 33396940, 2020). "The result is supported by the previous study where hs-CRP and IL-1RA levels were observed to be positively correlated with depressive symptoms in patients with type 2 diabetes (T2D)." (PMID 33061992, 2020). "In particular, serum ferritin levels resulted to be directly related to insulin-resistance and incident risk of type 2 diabetes mellitus (T2DM), independently of traditional risk factors, especially when high-sensitivity C reactive protein (hs-CRP) is increased." (PMID 32758229, 2020).
type 2 diabetes (continued). "In patients with other diseases associated with well-known pro-inflammatory responses such as Duchenne muscular dystrophy, type 2 diabetes, and peripheral neuropathy, elevated levels of CRP have been reported." (PMID 32943739, 2020). "In a study of 367 Mexican–Americans, type 2 diabetes was strongly related to elevated levels of IL-6, leptin, CRP and TNF-α, whereas higher glucose levels correlated positively and linearly with high levels of IL-6 and leptin." (PMID 32751810, 2020). "Another meta-analysis focusing on subjects with type-2 diabetes also concluded an inverse correlation between VitD and hs-CRP (hs-CRP drops by 0.034 mg/dL)." (PMID 32876941, 2020). "The control group had significantly lower Body Mass Index (BMI), waist circumference, blood pressure, fasting glucose and insulin concentrations, HOMA-IR, concentration of HbA1c, and C-reactive protein (CRP) than patients with type 2 diabetes." (PMID 32012942, 2020). "On the basis of these biological effects, this pilot study assessed the feasibility and potential efficacy of CCR2 inhibition by PG in terms of albuminuria as well as HbA1c and CRP levels in patients with type 2 diabetes and nephropathy." (PMID 32704573, 2020). "A previous study revealed that longer sleep duration (>9 h/day) was correlated with elevated CRP levels in women with type 2 diabetes." (PMID 31404954, 2019). "Serum CRP levels were significantly elevated in patients with prediabetes and those with type 2 diabetes compared with controls (p=0.004)." (PMID 31664423, 2019). "Increased levels of circulating inflammatory markers (i.e., C-reactive protein [CRP] and Interleukin-6 [IL-6]) predict body mass gain in older adults and type 2 diabetes." (PMID 30979048, 2019). "Increasing serum LPS or FFA levels were associated with higher Ln(hs‐CRP + 1) levels, Log(HOMA‐IR) levels and the prevalence of type 2 diabetes (P < 0.001)." (PMID 30950561, 2019). "The content of CRP in serum in obese patients exceeded that of control subjects, reaching the maximal values in patients with type 2 diabetes." (PMID 30871567, 2019). "Categorized CRP levels were elevated in patients with type 2 diabetes and prediabetes compared with controls." (PMID 31664423, 2019). "Exendin-based GLP-1 exenatide has been shown to reduce weight and glycosylated hemoglobin (HbA1c), systolic blood pressure, triglycerides, and high-sensitivity C-reactive protein (CRP) (hsCRP) in obese patients with type 2 diabetes." (PMID 31336911, 2019). "Associations have been suggested of high-dose ionising radiation exposure with type-2 diabetes and elevated levels of C-reactive protein, a marker of chronic inflammation." (PMID 30894578, 2019). "In our study, the rates of high CRP levels were 10/39 (25.6%) in controls, 15/43 (34.3%) in patients with prediabetes and 18/28 (64.3%) in patients with type 2 diabetes." (PMID 31664423, 2019). "CRP levels in patients with gestational diabetes (7.94 mg/L±5.95), diabetes type 1 (7.41 mg/L ± 4.55) and diabetes type 2 (6.96 mg/ L±4.43) were significantly higher than in non diabetic women (5.88 mg/L±4.91)." (PMID 32082531, 2019). "In this paper we investigated associations of several types of inflammatory disease morbidity (specifically hypothyroidism, hyperthyroidism, type-2 diabetes, rheumatoid arthritis, osteoarthritis) and CRP with previous RT exposure." (PMID 30894578, 2019). "Fasting and 2-h postprandial glucose and insulin, HbA1c, HOMA-IR, triglycerides, ALT and C-reactive protein (CRP) concentrations were significantly increased in subjects with IFG or type 2 diabetes compared to normal subjects (all Ps < 0.05)." (PMID 30532735, 2018). "Longitudinal studies of C-reactive protein, interleukin-6, tumor necrosis factor-α, fibrinogen, and plasminogen activator inhibitor-1 in type 2 diabetes." (PMID 29910771, 2018).
type 2 diabetes (continued). "An obesity low grade inflammatory state has been confirmed by the elevated levels of pro-inflammatory marker CRP a well-known harbinger of type 2 diabetes." (PMID 30200422, 2018). "There have been a small number of cross-sectional analyses performed regarding the relationship between circulating C-reactive protein, interleukin-6, fibrinogen, and type 2 diabetes." (PMID 29910771, 2018). "Although only observational in nature, these studies demonstrate that in patients with type 2 diabetes and diabetic kidney disease, circulating levels of C-reactive protein, fibrinogen, interleukin-6, and tumor necrosis factor are significantly increased." (PMID 29910771, 2018). "Cross-sectional studies of C-reactive protein, interleukin-6, and tumor necrosis factor-α in type 2 diabetes." (PMID 29910771, 2018). "Levels of ANGPTL4 are correlated with inflammatory markers including C-reactive protein and IL-1β in serum from patients with type 2 diabetes and breast cancer." (PMID 29563332, 2018). "Whilst women tended to show elevations in biomarkers related to an increased risk of type 2 diabetes (HOMA IR, leptin and TNF-α), men showed a marked increase in the cardiovascular disease risk biomarker CRP." (PMID 29190710, 2017). "In the same GWAS, several SNPs of NXPH1 were associated with type 2 diabetes, blood pressure and plasma LDL-cholesterol, HDL-cholesterol, TG as well as C-reactive protein levels." (PMID 28134766, 2017). "Among type 2 diabetes indicators, CRP measurement is a relatively inexpensive, standardised, and readily available measure." (PMID 28003714, 2016). "In a retrospective analysis of 110 obese patients with type 2 diabetes treated with liraglutide, the mean concentration of CRP declined after treatment with liraglutide for a mean duration of 7.5 months." (PMID 27110066, 2016). "The best model for ApN (R2 = 0.9002) obtained from stepwise regression in type 1 diabetes included CrCl, BMI, WBC, CRP, and age, while in type 2 diabetes the best model (R2 = 0.2882) included ppPG, LDL, and UA." (PMID 26089882, 2015). "In line with our current data previous findings obtained on hypertensive patients (with type 2 diabetes) treated with NAC experienced reduction of C-reactive protein, intracellular adhesion molecule, and vascular cell adhesion molecule." (PMID 25960622, 2015). "Our results indicated that significant increases in the levels of pro-inflammatory cytokines, TNF- α IL-6 and also CRP were observed in obese and type 2 diabetic rats and were consistent with other studies." (PMID 26003803, 2015). "ApN and HDL were significantly increased in type 1 diabetes in comparison with type 2 diabetes, whereas CRP, FIB, HCY, and GGT were significantly increased in DM2." (PMID 26089882, 2015). "The increased CRP level is a predictor of cognitive impairment in elderly patients with type 2 diabetes." (PMID 26578953, 2015). "On the other hand, plasma leptin levels are associated with vascular endothelial function in overweight patients with type 2 diabetes and leptin was found to be directly related to CRP independently of BMI and other confounding factors especially in men." (PMID 25994228, 2015). "Serum C-reactive protein (CRP) is a marker of systemic inflammation and has been shown to be associated with incident type 2 diabetes." (PMID 25994228, 2015). "C-reactive protein (CRP), a very sensitive and important inflammatory mediator, was been shown to be a valid predictor of new cardiovascular risks, type 2 diabetes, ischemic cerebrovascular disease, and PD." (PMID 26217177, 2015). "We did find a net lowering of CRP levels with atorvastatin 10 mg daily in patients with type 2 diabetes." (PMID 25899452, 2015). "CRP and IL-6, the two most sensitive markers of inflammation have been elevated in patients with type 2 diabetes." (PMID 26153197, 2015).
type 2 diabetes (continued). "High caffeinated coffee consumption was associated with lower plasma inflammatory parameters including E-selectin and C-reactive protein (CRP) in women with type 2 diabetes." (PMID 25338270, 2014). "In a prospective study in 2001, both C-reactive protein (CRP) and IL-6 were found to be predictive of the development of type 2 diabetes in obese patients." (PMID 25157251, 2014). "From our data we found a strong and graded association between CRP and UAE in patients with type 2 diabetes." (PMID 24350298, 2013). "Previous studies have shown positive correlation between sugar intake and CRP in rats, healthy adults, children, obese, and individuals with type 2 diabetes, suggesting several possible mechanisms." (PMID 24499591, 2013). "The inflammatory markers C-reactive protein and interleukin-6 were measured repeatedly and type 2 diabetes incidence (new cases) was monitored over an 18-year follow-up (from 1991–1993 until 2007–2009)." (PMID 23843750, 2013). "Elevated inflammatory biomarkers, such as C-reactive protein (CRP), have been consistently shown to increase the risk for clinical outcomes such as cardiovascular disease and type 2 diabetes." (PMID 24155956, 2013). "The purpose of the study was to find the correlation between platelet indices with fasting blood glucose, HbA1c and hs-CRP level in pathogenesis of vascular complications in type 2 diabetic patients." (PMID 24353529, 2013). "In persons with type 2 diabetes or impaired glucose tolerance, the correlation coefficient for CRP and IL-6 was reported to be in a similar range (r = 0.49)." (PMID 23991111, 2013). "A meta-analysis of n-3 and its effect on inflammatory factors from earlier studies found only two trials evaluating CRP on individuals with type 2 diabetes." (PMID 31667003, 2013). "The main objective was to determine the relationship between the glycemic control, platelet indices and CRP levels in patients of type II diabetes." (PMID 24353529, 2013). "A recent study has proved that elevated serum MBL in patients with type 2 diabetes indicates poor diabetic control and development of diabetic nephropathy, especially in combination with serum CRP." (PMID 24376633, 2013). "In contrast, the strongest evidence for a relationship between CRP and type II diabetes occurred at those thresholds where the variance explained in CRP was at a minimum, suggesting a spurious relationship between the two variables." (PMID 24204319, 2013). "In cases of moderate upregulation of circulating levels of CRP and IL-6, such as in subclinical systemic inflammation of type 2 diabetes, this is usually accompanied by increased concentrations of soluble adhesion molecules." (PMID 23991111, 2013). "Systemic markers in type 2 diabetes are shifted towards a more pro-inflammatory status, including elevated C-reactive protein (CRP) and fibrinogen levels and greater numbers and a more activated state of various leukocyte populations." (PMID 22929089, 2012). "Serum levels of the inflammatory markers (IL-6, hs-CRP, Hp) were significantly increased (p = .000.019, and .000 respectively) in type 2 diabetics compared to control subjects." (PMID 23283045, 2012). "Keywords used in the search were combinations of the “diet,” “chronic inflammation,” “type 2 diabetes,” “C-reactive protein,” “interleukins,” and “tumor necrosis factor” (TNF)." (PMID 23316349, 2012). "In this report, we have shown significantly higher serum concentrations of inflammatory markers (IL-6, hs-CRP, and Hp) in type 2 diabetics compared to controls." (PMID 23283045, 2012). "On univariate analysis, participants who developed type 2 diabetes had significantly higher baseline levels of IL-6, CRP, leptin and γGT, and lower levels of adiponectin than participants who remained free of type 2 diabetes." (PMID 23251619, 2012).
type 2 diabetes (continued). "Participants who developed type 2 diabetes during follow-up had significantly higher levels of IL-6, hs-CRP, leptin and γGT, and lower levels of adiponectin than participants who remained free from type 2 diabetes." (PMID 23251619, 2012). "In type 2 diabetics, serum concentrations of IL-6, hs-CRP, and Hp were significantly elevated and correlated to body mass index." (PMID 23283045, 2012). "Since then more studies have shown increased levels of inflammatory mediators like C-reactive protein, interleukin-6, and plasminogen activator inhibitor-1 in patients with type-2 diabetes." (PMID 22792473, 2012). "On the contrary, one randomized trial in participants with type 2 diabetes showed that reduction in CRP concentration after 1 year was more pronounced in a low GI diet than a high GI diet." (PMID 21804937, 2011). "HW has also been proposed to be an important factor increasing C-reactive protein (CRP) concentrations and relative coronary risk in patients with type 2 diabetes of any age and sex." (PMID 21477296, 2011). "In patients with type 2 diabetes, the use of Anakinra (IL-1Ra) improved glycemia and beta-cell secretory function and reduced markers of systemic inflammation (CRP, IL-6)." (PMID 21410952, 2011). "In patients with type 2 diabetes, treatment with rimonabant at the highest dose (20 mg) decreased CRP (-26%) and leptin (-2%)levels." (PMID 21276223, 2011). "Several studies have reported that lower plasma adiponectin as well as higher levels of cytokines and C-reactive protein (CRP), coexist in type 2 diabetes and are contributory factors for developing cardiovascular disease." (PMID 20490354, 2010). "In type-2 diabetes, levels of multiple inflammatory markers (CRP, IL-6, adhesion molecules) are elevated in an early disease stage and increased further with disease progression." (PMID 20178593, 2010). "Adults of South Asian origin living in the United Kingdom have high risks of type 2 diabetes and central obesity; raised circulating insulin, triglyceride, and C-reactive protein concentrations; and low HDL-cholesterol when compared with white Europeans." (PMID 20421924, 2010). "First, since the current study was cross-sectional, it was not possible to establish the causality between elevated serum CRP/GGT and type 2 diabetes." (PMID 21076541, 2010). "Adults of African-Caribbean origin living in the UK have smaller increases in type 2 diabetes risk, raised circulating insulin and HDL-cholesterol, and low triglyceride and C-reactive protein concentrations." (PMID 20421924, 2010). "Prospective studies have found that the development of increased urinary albumin excretion is preceded by elevated levels of inflammation markers: CRP in a general white population and both CRP and fibrinogen in persons with type 2 diabetes." (PMID 21054877, 2010). "After adjustment for HOMA-IR and hs-CRP, ALT [OR: 3.62(1.37–9.53)] and GGT [OR: 2.70(1.15–6.35)] were independently associated with type 2 diabetes." (PMID 18533046, 2008). "However, the fact that adjustment for CRP had minor effect on the association of GGT with incident type 2 diabetes may indicate that GGT might also be involved in the pathogenesis of type 2 diabetes through non-inflammatory mechanisms related to oxidative stress." (PMID 18533046, 2008). "In the FinnishDiabetes Prevention Study, hs-CRP was the best immunological predictorfor the progression from impaired glucose tolerance to overt type-2diabetes." (PMID 18288276, 2007). "Several studies have suggested that type 2 diabetes is an inflammatory condition, mainly due to finding increased levels of inflammatory markers such as C-reactive protein and IL-6 in type 2 diabetics." (PMID 23675048, 2007). "The purpose of this study was to evaluate the clinical value of serum glycated albumin and high-sensitivity C-reactive protein (hs-CRP) levels in predicting the presence of CAD in patients with type 2 diabetes." (PMID 17178005, 2006).